ALB (albumin)
Diseases named in the same sentence as ALB in open-access papers (continued):
Sharing a sentence is not in itself a finding about the gene and the disease.
malnutrition (continued). "As malnutrition biomarkers, ALB, PA and TRF have been widely used for nutritional status evaluation after operation." (PMID 33690172, 2021). "Malnutrition, inflammatory status, and cachexia caused by the presence of a neoplasm are typically mirrored by lower protein synthesis, so that the predictably low serum albumin concentration could be associated with high postoperative mortality, as reported for several cancers." (PMID 34298807, 2021). "Malnutrition and inflammation suppress the synthesis of serum ALB, which can reflect the nutritional status of patients, as well as the severity, progression, and prognosis of disease." (PMID 34992504, 2021). "Hypoalbuminemia refers to serum albumin level lower than 3.5 g/dL, which is regarded as a marker of malnutrition in trauma patients." (PMID 33510388, 2021). "Serum albumin concentration is the most commonly used serum marker of malnutrition, in which patients are considered to be malnourished when serum albumin concentrations are <35g/L." (PMID 34016037, 2021). "In the present study, we measured total proteins, albumin and lymphocytes as indirect indicators of malnutrition, considering the inflammatory status of the patients detected by the nursing homes by means of blood tests." (PMID 34342076, 2021). "We identified the top-ranking variables associated with PPOLOS for major cancers and confirmed that the following factors correlated with PPOLOS: malnutrition (albumin and globulin), cancer stage, type of surgery, pulmonary function, and BMI." (PMID 33616544, 2021). "Low pre‐dialytic serum creatinine reflects lower muscle mass, and it as well as low serum albumin indicate malnutrition or inanition." (PMID 34132036, 2021). "Serum albumin level and BMI at admission and after surgery were all significantly lower as the malnutrition status getting worse." (PMID 34246241, 2021). "Anemia (hematocrit <35%) was observed in 16.4%, whileprotein malnutrition (albumin <3.5 mg/dl) was present in 7.3%." (PMID 33470377, 2021). "Next, we performed the multivariable logistic regression analysis adjusted for age, body weight right before treatment and serum albumin level to predict moderate and severe malnutrition status in patients with different gynecological cancer." (PMID 35127741, 2021). "Together, these data demonstrate that only the LP 3% diet was able to induce malnutrition in mice characterized by the decrease in body mass, serum albumin, hemoglobin levels and food consumption, all indicators of a nutritional deficiency." (PMID 33815321, 2021). "Older people with low albumin levels can show loss of muscle mass, and hypoalbuminemia is sometimes considered to be an indicator of malnutrition, but there are other factors that affect serum albumin levels." (PMID 33925831, 2021). "Although the correlation of albumin levels with malnutrition provides a rationale for its clinical implementation, it is troublesome to define the cutoff value, especially in elderlies." (PMID 33673556, 2021). "Decreased albumin synthesis, increased catabolism, and aggravated inflammation contribute to malnutrition." (PMID 34316292, 2021). "The M/E was highly negatively correlated to a number of comorbidities, malnutrition (as assessed by p-albumin), and inflammation (C-reactive protein)." (PMID 34743686, 2021). "For example, problems with the secretion of lymphocytes, albumin, and cytokines during periods of malnutrition and secretion of leptin in the context of sepsis." (PMID 34382503, 2021). "Body weight, concentration of hemoglobin in whole blood, and concentration of total protein and albumin in serum, were measured in animals from Control (Ctrl) and experimental groups (LP 3% and LP 8%, LF 2.5% and 5%) to verify malnutrition status." (PMID 33815321, 2021).
malnutrition (continued). "Presence of endometrial and cervical cancer, body weight before nutritional intervention and serum albumin level (P < 0.001 for all) were found to be significant predictors for malnutrition status in gynecological cancer patients." (PMID 35127741, 2021). "PNI is a valuable malnutrition parameter obtained by adding five times the lymphocyte counts to the serum albumin value." (PMID 33355787, 2021). "The improvement of pre-albumin thanks to IDPN was in fact more evident in patients with moderate malnutrition (SGA stage B) than those with severe malnutrition (SGA stage C)." (PMID 33406683, 2021). "Malnutrition will further aggravate liver damage, significantly reduce the frequency of albumin synthesis, and increase the incidence of complications such as hypoproteinemia, infection, and poor healing, thus slowing the recovery of patients after surgery." (PMID 34518766, 2021). "Biomarkers of systemic inflammation and malnutrition, such as albumin, are firmly established as having a prognostic value in patients with cancer." (PMID 34660664, 2021). "Serum albumin is an objective parameter that is closely correlated with the degree of malnutrition, and a decrease in serum albumin level during or after definitive chemoradiotherapy has been reported as a poor prognostic factor in oesophageal cancer patients." (PMID 33590710, 2021). "The usefulness of serum albumin levels, total cholesterol levels, and blood lymphocyte counts as markers for the screening of malnutrition has been shown." (PMID 33918066, 2021). "When inflammation becomes chronic, ALB synthesis is reduced in the liver, indicating malnutrition and cachexia in cancer cases." (PMID 33550761, 2021). "Serum albumin is an important parameter in clinical assessment of nutritional status of patients, and hypoalbuminemia is considered as a marker of malnutrition-inflammatory response syndrome." (PMID 34861893, 2021). "In particular, the reduced albumin content in serum can serve as a sign of malnutrition and systemic inflammation." (PMID 34820414, 2021). "Clinically, albumin levels are often used as a serologic marker of nutritional status, with low albumin levels representing malnutrition, although several studies have shown that albumin is an inconsistent measure of nutritional status." (PMID 33592030, 2021). "Serum protein levels (albumin, prealbumin, transferrin, and retinol-binding protein) alone cannot be used as an indicator of malnutrition, as their production is influenced by hepatic disease, sepsis, inflammation, and hydration status." (PMID 34444944, 2021). "In Japan, serum albumin levels are used to assess malnutrition risks among individuals aged ≥65 years old." (PMID 34813604, 2021). "The albumin level reflects the nutrition status, suggesting a relation between UP and malnutrition–inflammation complex syndrome." (PMID 34822553, 2021). "It was confirmed that ECW and malnutrition-related blood chemistry findings, including hemoglobin, serum total protein, serum albumin, serum creatinine, serum phosphorus, and serum potassium, were important features." (PMID 33891656, 2021). "Assessment of malnutrition status among VL patients and control groups was performed using anthropometric techniques and biochemical tests (serum albumin and total protein) through standard kit measurement method." (PMID 34797863, 2021). "Low serum albumin levels are considered as a sensitive and classic marker of malnutrition combined with inflammation in PD patients." (PMID 34592885, 2021). "Malnutrition and an increased turnover of albumin by tumors adds up to lower albumin levels observed in cancer patients." (PMID 34884980, 2021). "Only 1 patient (0.8%) had hypoproteinemia, showed the importance of albumin is questioned in malnutrition evaluation among locally advanced NPC patients." (PMID 33763439, 2021).
malnutrition (continued). "During the first trimester, women who would later have a preterm delivery tended to have lower BUN, albumin, and phosphorus levels, suggesting that they had malnutrition." (PMID 34591251, 2021). "The albumin and total protein concentrations in the plasma were significantly lower in the malnutrition group than those in the control group." (PMID 33650806, 2021). "Albumin is a protein synthetized in the liver, and a serum concentration under 3.5 g/dL is considered representative of malnutrition." (PMID 34640525, 2021). "The cause of abnormal ALB and ALP include malnutrition, benign liver disease, and renal dysfunction, among others." (PMID 34539891, 2021). "ALB is recognized as an indicator for nutrition status, which is decreased in serious malnutrition, chronic inflammatory, and autoimmune diseases." (PMID 34234877, 2021). "Although we didn’t found the report on SCFAs and albumin directly related, there were a few studies on SCFAs and malnutrition." (PMID 34082732, 2021). "Albumin, as an indicator of malnutrition in the elderly in clinically stable conditions, was recorded within normal ranges." (PMID 34835952, 2021). "Patients with preoperative low level of albumin showed malnutrition or diminished strength, making them less tolerate surgery." (PMID 34717707, 2021). "Recent studies have investigated the albumin/globulin ratio (al/gl-ratio) in malnutrition, suggesting an impaired al/gl-ratio as an index of malnutrition." (PMID 34070968, 2021). "As another inflammatory index, decreased albumin levels represent a marker for malnutrition and systemic inflammation." (PMID 33179214, 2021). "The final analysis, also including 62 autologous transplanted patients (total number 100) identified lower albumin, total proteins, and transferrin as useful biomarkers for malnutrition, worsening of performance status, and mucositis onset." (PMID 33488571, 2020). "Albumin is a positive marker for malnutrition, but we considered the high levels of serum albumin to be independent in the PPD-positive control group." (PMID 32323130, 2020). "Patients with hidden hypocalcemia were likely to be older and had lower BMI and albumin levels, and higher pH than patients with apparent hypocalcemia, suggesting malnutrition (P < 0.05)." (PMID 32157180, 2020). "Patients with albumin levels ≤ 35 g/L, corresponding to moderate malnutrition, were exposed to a higher postoperative morbidity (29.17% vs 70.83%, p = 0.002)." (PMID 32107426, 2020). "On the other hand, our attention was on malnutrition, and hence, we estimated the levels of albumin, total protein, transferrin, and prealbumin." (PMID 32490516, 2020). "mGPS is calculated from C-reactive protein (CRP) and serum albumin, a common marker of malnutrition and inflammation, and PNI is calculated from serum albumin and total peripheral lymphocyte count." (PMID 33176752, 2020). "The median of malnutrition indicator albumin in our series was 37.1 g/l and only two patients were lower than the normal level." (PMID 32438931, 2020). "Assessment of malnutrition status indicated that serum albumin concentration significantly increased in the intervention group compared to the baseline." (PMID 32807165, 2020). "Common markers of malnutrition that have been studied include low serum albumin as a marker of protein status, low total lymphocyte count (TLC), and an excessively high or low body mass index (BMI)." (PMID 32660593, 2020). "However, serum albumin levels should be used with caution as nutritional markers for these patients, because low levels of this protein in HD patients are also associated with malnutrition, inflammation and, consequently, with other complications such as anemia secondary to ESRD." (PMID 33228547, 2020). "Lower serum albumin concentration was also proved to have a close connection to bad clinical outcomes in patients with CAD mainly due to malnutrition and inflammation." (PMID 32934964, 2020).
malnutrition (continued). "Nutritional support for HCC patients significantly increases the serum albumin level, reduces the incidence of ascites or peripheral edema, and contributes to the improvement in malnutrition." (PMID 32280472, 2020). "Among the numerous methods to define malnutrition, the one most frequently used is the serum albumin level." (PMID 33203417, 2020). "Serum albumin was chosen as a surrogate marker of malnutrition in this study because hypoalbuminemia is the single most important marker of malnutrition and mortality in dialysis patients." (PMID 32351809, 2020). "Albumin is a well-known plasma protein with multiple physiological functions; the level of this protein fluctuates during inflammation and malnutrition." (PMID 33521032, 2020). "GNRI score is calculated using the serum albumin level and BW, and malnutrition defined by GNRI was a useful prognostic indicator in chronic HF patients." (PMID 33137941, 2020). "The study by Huang et al14 is the only study that describes malnutrition as low albumin or transferrin in the second half of the study." (PMID 33939393, 2020). "In the group of patients without malnutrition and with moderate malnutrition, the concentration of albumin was significantly higher than in patients with severe malnutrition (SGA A vs. B or C) (3.4 vs. 3.2 g/l; p < 0.0011)." (PMID 33327591, 2020). "Malnutrition defined by low GNRI was associated with lower serum Cr, whereas malnutrition defined by a low Cr index was associated with lower serum albumin." (PMID 32238848, 2020). "In patients with good nutritional status, significantly higher albumin values were noted compared to subjects with moderate or severe malnutrition (SGA A vs. B or C) (3.8 vs. 3.3 g/l; p < 0.0001)." (PMID 33327591, 2020). "Given the worrying albumin values obtained during hospitalization, the need to personalize the nutritional approach in the hospital is emphasized as it is an index of malnutrition and wasting of patients." (PMID 33261019, 2020). "This suggests that albumin concentration cannot be used in diagnosis of malnutrition, though it remains a useful tool in assessment of prognosis in CHF patients." (PMID 32759722, 2020). "Low serum albumin levels, low prealbumin levels, and low BMI are commonly used indicators for the evaluation of malnutrition in patients." (PMID 31410742, 2020). "Malnutrition was measured using serum markers (albumin <3.5 g/dL) as well as body mass index (BMI) as a marker of obesity (BMI > 30 kg/m2)." (PMID 32029855, 2020). "Thanks to this, it is possible to evaluate the relationship of albumin with some solid tumors (colorectal, gastric, pancreas, etc.)and the state of inflammation and malnutrition." (PMID 33261019, 2020). "Low albumin concentration is one of the predictors of malnutrition and its decrease in IBD patients, particularly in the active phase of the disease, is likely to reflect the disease-associated worsening of nutritional status." (PMID 32824619, 2020). "There were 13 (2.4%) patients with malnutrition before surgery (preoperative albumin < 3.5 g/dL), 314 (56.4%) patients with albumin < 3.5 g/dL within 7 days after surgery, and 114 (20.6%) patients with albumin < 3.0 g/dL within 7 days after surgery." (PMID 33203417, 2020). "Transferrin and hemopexin are involved in the transport and storage of iron, and they often decline together with albumin during acute-phase reactions and malnutrition." (PMID 32472529, 2020). "Malnutrition can be screened using serum albumin levels, SGA scores by dietitian’s interview, BIA data, and other methods." (PMID 32711448, 2020). "For example, albumin, the most abundant protein in human serum, has been used as an indicator of malnutrition in elderly people." (PMID 33166358, 2020). "The study by Yi et al26 is the only study that describes malnutrition as low albumin or transferrin or TLC in the second half of the study." (PMID 33939393, 2020).
malnutrition (continued). "Concerning simple parameters of malnutrition, our analyses revealed a statistically significant inverse association of NUTRIC and mNUTRIC with albumin (p = 0.008 vs. p = 0.013)." (PMID 32709104, 2020). "According to the BMI or ALB results, the hospitalization time of the malnutrition group was slightly longer than that of normal nutrition group." (PMID 32092109, 2020). "Previous literature already reported a significant reduction of serum albumin, Hb and 25(OH)D concentrations that are recognized malnutrition biomarkers." (PMID 32492873, 2020). "Increased serum CPR levels indicate systematic inflammation status and low serum albumin levels indicate malnutrition and cachexia." (PMID 32314876, 2020). "Accordingly, decreased functional level can lead to eating disorders, which deteriorate nutritional status and lead to malnutrition and reduced albumin concentration." (PMID 33157940, 2020). "Albumin levels are relatively stable in healthy women but can decline in several conditions, including malnutrition and malabsorption." (PMID 32723677, 2020). "Traditional markers of malnutrition such as serum albumin (Alb), prealbumin (PA), hemoglobin (Hb), transferrin (TRF), and body mass index (BMI) are influenced not only by nutritional status but also by age, gender, inflammation status, and liver function." (PMID 33511142, 2020). "However, due to high mortality and poor general condition related to the high risk of malnutrition, there were a considerable number of missing data regarding body weight and albumin, more than two months after procedure; yet several studies have used albumin inevitably as a nutritional marker." (PMID 32927691, 2020). "Albumin levels indicate the malnutrition status of an individual as well as implicate the existence of inflammation." (PMID 33014783, 2020). "This negative association between serum albumin and protein carbonyl levels supports the well-established theory that a low serum albumin level reflects the presence of systemic inflammation and oxidative stress as well as malnutrition or malabsorption." (PMID 32677905, 2020). "NRI is a screening tool that predicts patient’s malnutrition status, based on serum albumin, as well as, on current and usual body weight." (PMID 32785121, 2020). "Serum albumin levels were notably within the normal range, notwithstanding their marked malnutrition." (PMID 32582446, 2020). "Its potential in clinical practice is substantiated by its relationship with established measures of frailty such as serum albumin levels, which play a prominent role in the estimation of frailty by reflecting the extent of muscle weakness and malnutrition." (PMID 33055057, 2020). "Under MV, the body is under stress conditions associated with robust energy consumption, metabolism, and decomposition activity, which can lead to relative malnutrition, manifested by a decreased plasma albumin level." (PMID 32257085, 2020). "Low albumin levels reflect malnutrition and an impaired ability of protein synthesis in the liver, i.e., impaired liver function." (PMID 33129309, 2020). "Lower albumin levels in patients with lower PNI reflects malnutrition and impaired protein synthesis ability in livers with chronic inflammation and fibrosis due to the underlying liver disease." (PMID 33129309, 2020). "Previous studies showed that low serum albumin concentration was a strong prognostic marker for many diseases, mainly due to malnutrition and inflammation." (PMID 32934964, 2020). "Decreases in albumin are reflective of malnutrition, suggesting that the immune ability is weakened, leading to an increased risk of infection and tumour progression, which is related to poor tumour-related prognosis." (PMID 32184816, 2020). "A low albumin can be an indicator of poor general health and malnutrition, however, this is less likely to explain our findings since as both groups in our cohort had a comparable BMI of ~30 Kg/m2." (PMID 31936687, 2020).